RBPMS (RNA binding protein, mRNA processing factor)
Description:
[Isoform A]: RNA binding protein that mediates the regulation of pre-mRNA alternative splicing (AS). Acts either as activator (FLNB, HSPG2, LIPA1, MYOCD, PTPRF and PPFIBP1) or repressor (TPM1, ACTN1, ITGA7, PIEZO1, LSM14B, MBNL1 and MBML2) of splicing events on specific pre-mRNA targets (By similarity). Together with RNA binding proteins RBFOX2 and MBNL1/2, activates a splicing program associated with differentiated contractile vascular smooth muscle cells (SMC) by regulating AS of numerous pre-mRNA involved in actin cytoskeleton and focal adhesion machineries, suggesting a role in promoting a cell differentiated state (By similarity). Binds to introns, exons and 3'-UTR associated with tandem CAC trinucleotide motifs separated by a variable spacer region, at a minimum as a dimer. The minimal length of RNA required for RBPMS-binding tandem CAC motifs is 15 nt, with spacing ranging from 1 to 9 nt. Can also bind to CA dinucleotide repeats. Mediates repression of TPM1 exon 3 by binding to CAC tandem repeats in the flanking intronic regions, followed by higher-order oligomerization and heterotypic interactions with other splicing regulators including MBNL1 and RBFOX2, which prevents assembly of ATP-dependent splicing complexes (By similarity). [Isoform C]: Acts as a regulator of pre-mRNA alternative splicing (AS) (By similarity). Binds mRNA. Regulates AS of ACTN1, FLNB, although with lower efficiency than isoform A / RBPMSA (By similarity). Acts as coactivator of SMAD transcriptional activity in a TGFB1-dependent manner, possibly through increased phosphorylation of SMAD2 and SMAD3 at the C-terminal SSXS regions and promotion of the nuclear accumulation of SMAD proteins.
Synonyms: Hermes
Tractability: PROTAC: ubiquitination databases record sites on it.
Gene: Protein-coding gene on chromosome 8 (30,384,416 to 30,572,256, forward strand). Ensembl gene ENSG00000157110.
Subcellular location: Nucleus; Cytoplasm; Cytoplasm, Stress granule; Cytoplasm, P-body
Subcellular location (Human Protein Atlas): Nucleoplasm; Cytosol
Gene Ontology:
Molecular function: mRNA 3'-UTR binding; mRNA CDS binding; pre-mRNA intronic binding; protein binding; protein homodimerization activity; RNA binding; transcription coactivator activity; molecular adaptor activity; identical protein binding; nucleic acid binding; pre-mRNA binding
Biological process: response to oxidative stress; SMAD protein signal transduction; protein-containing complex assembly; regulation of alternative mRNA splicing, via spliceosome; RNA processing; positive regulation of DNA-templated transcription
Cellular component: cytoplasm; cytoplasmic stress granule; cytosol; nucleoplasm; nucleus; P-body
Genetic constraint (gnomAD): Loss-of-function variants: 6 observed, 16.15 expected, observed/expected ratio (o/e) 0.37, 90% interval 0.2 to 0.73. The upper end of that interval is the gene's LOEUF score, 0.73, which puts it in group 3 of 6, group 1 being the genes least tolerant of losing a copy. Missense variants: 149 observed, 173.13 expected, observed/expected ratio (o/e) 0.86, 90% interval 0.75 to 0.99. Synonymous variants: 72 observed, 66 expected, observed/expected ratio (o/e) 1.09, 90% interval 0.9 to 1.33.
Homologues: Orthologues: mouse Rbpms (99% identical), dog RBPMS (92% identical), chimpanzee RBPMS (91% identical), macaque RBPMS (91% identical), rabbit RBPMS (91% identical), pig RBPMS (91% identical), guinea pig RBPMS (90% identical), tropical clawed frog rbpms (82% identical), rat Rbpms (75% identical), zebrafish rbpms (58% identical), Caenorhabditis elegans mec-8 (45% identical). Paralogues in human: RBPMS2 (69% identical).
Diseases named in the same sentence as RBPMS in open-access papers:
RBPMS is named in the same sentence as 36 diseases in open-access papers, as found by Europe PMC text mining. Sharing a sentence is not in itself a finding about the gene and the disease. The quoted sentences say what the papers report.
ovarian carcinoma (7 papers, 2016 to 2024). A malignant neoplasm originating from the surface ovarian epithelium. "For example, matrix metalloproteinase 3 (MMP3), one of the most increased transcripts upon RBPMS knockout, has been linked with the metastatic potential of various cancer types as well as cisplatin resistance in ovarian cancer cells." (PMID 35008958, 2022). "ATP11, which was increased upon RBPMS knockout here, has also been associated with cisplatin resistance in ovarian cancer." (PMID 35008958, 2022). "In the present study, we investigated the role of the RBPMS splice variants in ovarian cancer cells and mouse models." (PMID 36499073, 2022). "RBPMS knockout has been associated with increased invasion ability in ovarian cancer." (PMID 36499073, 2022). "However, little is known about the biological role of the RBPMS splice variants in ovarian cancer cells." (PMID 36499073, 2022). "Therefore, further studies are needed to confirm the biological role of these RBPMS downstream genes and their diagnostic, prognostic and/or therapeutic potential in ovarian cancer." (PMID 36499073, 2022). "Together, this information suggests that RBPMS could represent a novel diagnostic, prognostic, and response-to-therapy marker in ovarian cancer." (PMID 35008958, 2022). "RBPMS and its regulated genes may be considered as diagnostic, prognostic, and/or response to therapy biomarkers in ovarian cancer." (PMID 35008958, 2022). "Moreover, proliferation and invasion of ovarian cancer cells could be impeded by inhibiting microRNA-21-associated target genes that included RBPMS, RCBT1 and ZNF608." (PMID 31084621, 2019). "We observed that RBPMS levels were significantly lower (* p < 0.05) in the ovarian cancer patients when compared with the normal ovarian controls." (PMID 35008958, 2022). "In summary, the major finding of this study was that RBPMS knockout increased the proliferation and invasion ability of ovarian cancer cells as well as their senescence." (PMID 35008958, 2022). "We also found that the RBPMS expression levels were reduced in ovarian cancer patients and in cisplatin-resistant ovarian cancer cells when compared with normal ovaries and cisplatin-sensitive cells, respectively." (PMID 35008958, 2022). "We previously reported that reduced RBPMS levels decreased the sensitivity of ovarian cancer cells to cisplatin treatment." (PMID 36499073, 2022). "Previously, we reported that the RNA binding protein with multiple splicing (RBPMS) is a miR-21-3p target gene in cisplatin-resistant ovarian cancer cells." (PMID 35008958, 2022). "RBPMS knockout promoted cell proliferation, invasion, and increased the cisplatin resistance of ovarian cancer cells." (PMID 35008958, 2022). "Decreased RBPMS expression also reduced the sensitivity of the ovarian cancer cells to cisplatin treatment." (PMID 35008958, 2022). "Using the GEPIA cancer patient database, we observed that the RNA levels of RBPMS were lower in ovarian cancer patients as compared with normal ovary samples." (PMID 35008958, 2022). "The RBPMS levels also correlated with the response to therapy, with ovarian cancer patients with higher levels of RBPMS having greater PFS than those with lower RBPMS levels." (PMID 35008958, 2022). "KM curves constructed by GEPIA showed that the OS and disease-free survival (DFS) rates were significantly lower in the ovarian cancer patients with lower RBPMS expression levels." (PMID 35008958, 2022). "Together, this information suggests that RBPMS regulates the expression of genes via the self-renewal capacity as well as invasion and metastasis in ovarian cancer cells." (PMID 35008958, 2022).
ovarian carcinoma (continued). "Programmed cell death 4 (PCDC4), a tumor suppressor gene reduced in many cancer types—including ovarian cancer —was also reduced upon RBPMS knockout." (PMID 35008958, 2022). "Together, these results suggested that reduced levels of RBPMS increased the cell proliferation and invasion ability and reduced the sensitivity of the ovarian cancer cells to cisplatin treatment." (PMID 35008958, 2022). "The CRISPR-mediated RBPMS knockdown of the protein levels in the ovarian cancer cells induced long-term effects in terms of cell proliferation, as evidenced by the clonogenic assays." (PMID 35008958, 2022). "We previously reported that CRISPR-mediated RBPMS knockdown reduced the sensitivity of ovarian cancer cells to cisplatin treatment." (PMID 36499073, 2022). "Reduced protein levels of RBPMS have been documented in bladder cancer, multiple myeloma, ovarian cancer, and osteoarthritic cartilage cell lines." (PMID 36499073, 2022). "The potential role of RBPMS as a tumor suppressor gene in ovarian cancer should be further investigated." (PMID 35008958, 2022). "In a Western blot, we observed that the RBPMS levels were dramatically lower in the cisplatin-resistant compared with the cisplatin-sensitive ovarian cancer cells." (PMID 35008958, 2022). "Recently we published that reduced RBPMS levels increase the sensitivity of ovarian cancer cells to cisplatin treatment." (PMID 36499073, 2022). "This database also showed that the RNA levels of RBPMS correlated well with the OS of the disease, with ovarian cancer patients with higher RBPMS RNA expression levels living longer than those with lower RBSPMS levels." (PMID 35008958, 2022). "We observed that the RBPMS protein levels were lower in the ovarian cancer ovaries compared with the normal ovaries." (PMID 35008958, 2022). "We also observed that the knockdown of RBPMS reduced the sensitivity of the ovarian cancer cells to cisplatin treatment." (PMID 35008958, 2022). "We took advantage of the Gene Expression Profiling Interactive Analysis (GEPIA) searchable database (RNAseq data) to investigate the RBPMS RNA expression in 426 ovarian cancer patients and 88 normal ovarian patients (controls)." (PMID 35008958, 2022). "The major finding of this study was that the CRISPR-mediated RBPMS knockdown promoted cell proliferation and invasion as well as increased the cisplatin resistance of ovarian cancer cells." (PMID 35008958, 2022). "Using Internet search tools and an ovarian cancer tissue array, we studied correlations between RBPMS expression levels and ovarian cancer patient outcomes." (PMID 35008958, 2022). "Accordingly, we interrogated available Internet databases and found that ovarian cancer patients with high RBPMS levels live longer compared to patients with low RBPMS levels." (PMID 35008958, 2022). "To assess if the differentially expressed RNA transcripts identified upon RBPMS knockout are clinically relevant in ovarian cancer, we conducted a survival analysis using the KM plotter." (PMID 35008958, 2022). "On the other hand, most ovarian cancer epithelial cells showed moderate or negligible RBPMS staining." (PMID 27166999, 2016). "Further studies are needed to clarify the biological role and the clinical significance of RBPMS in ovarian cancer." (PMID 27166999, 2016). "SiRNA-induced RBPMS silencing reduced the sensitivity of ovarian cancer cells to cisplatin treatment." (PMID 27166999, 2016). "Future studies are needed to confirm the RBPMS protein expression patterns in ovarian cancer patients." (PMID 27166999, 2016). "We observed that the reduced expression of RBPMS increased cell growth and reduced sensitivity of ovarian cancer cells to cisplatin treatment." (PMID 27166999, 2016). "A2780 ovarian cancer cells expressed lower levels of miR-21-3p and higher levels of RBPMS, RCBTB1, and ZNF608 as compared to A2780CP20 cells." (PMID 27166999, 2016).
ovarian carcinoma (continued). "Moreover, β-galactosidase (β-Gal) measurements showed that RBPMS knockdown induced senescence in ovarian cancer cells." (PMID 35008958, 2022). "Similarly, immunohistochemical (IHC) analysis in a tissue array of ovarian cancer patient samples showed that serous ovarian cancer tissues showed weaker RBPMS staining when compared with normal ovarian tissues." (PMID 35008958, 2022). "Our finding that the RBPMS protein levels in cisplatin-resistant ovarian cancer cells were considerably lower than in their sensitive counterparts suggested that this protein could play a key role in cisplatin resistance." (PMID 35008958, 2022). "Based on the observed reduced expression of RBPMS in the cisplatin-resistant ovarian cancer cells, we next aimed to determine whether RBPMS knockout reduced the sensitivity of ovarian cancer cells to cisplatin treatment." (PMID 35008958, 2022). "Therefore, it is important to elucidate which of the RBPMS downstream pathways reported here are responsible for the increasing senescence in cisplatin-resistant ovarian cancer." (PMID 35008958, 2022). "Interrogation of the Kaplan–Meier (KM) plotter database identified multiple downstream-RBPMS effectors that could be used as prognostic and response-to-therapy biomarkers in ovarian cancer." (PMID 35008958, 2022). "Until now, little has been known about the biological function of RBPMS in ovarian cancer." (PMID 35008958, 2022). "Overall, our findings provide new evidence indicating that reduced levels of RBPMS contribute to the cell growth and invasion as well as drug resistance of ovarian cancer cells as well as that RBPMS could act as a tumor suppressor gene in these cells." (PMID 35008958, 2022). "However, the role of each RBPMS splice variant in ovarian cancer cells had not been studied previously." (PMID 36499073, 2022). "However, the biological role of RBPMS in ovarian cancer and/or the cisplatin resistance of ovarian cancer cells is unknown." (PMID 35008958, 2022). "Thus, increasing the RBPMS levels could have the potential to take out cells of senescence stages, and reduce the cell growth and proliferation of cisplatin resistant ovarian cancer cells." (PMID 36499073, 2022). "However, the role of each RBPMS splice variant in ovarian cancer cells has not been previously studied." (PMID 36499073, 2022). "Furthermore, the deregulation of other downregulated genes following RBPMS knockout, including PDGFD, TES, CARD16, and KNF521, has been linked to the progression of many cancer types, and the role of these genes in the ovarian cancer setting should be investigated." (PMID 35008958, 2022). "Following RBPMS knockout, the expression levels of TPH2, DCN, TRHD2, LUM, and SERPINE1 were in agreement with the survival outcomes: The PFS and OS were worse in ovarian cancer patients with higher levels of these transcripts." (PMID 35008958, 2022). "Of the 19 predicted miR-21-3p target genes analyzed, only three genes (RBPMS, RCBTB1 and ZNF608) were confirmed as miR-21-3p target genes in ovarian cancer cells." (PMID 27166999, 2016). "As for the human data, we acknowledge that the number of ovarian cancer samples analyzed by IHC is not optimal to reach a definite conclusion on the role of RBPMS in ovarian cancer." (PMID 27166999, 2016). "In addition, we identified RBPMS, RCBTB1 and ZNF608 as targets of miR-21-3p in cisplatin-resistant ovarian cancer cells." (PMID 27166999, 2016). "The upregulation of FOXL2 (downregulated upon RBPMS knockout) has been found to suppress cervical cancer cell proliferation and facilitate the apoptosis of these cells; thus, it could be important to study the role of FOXL2 in ovarian cancer." (PMID 35008958, 2022). "However, the molecular effectors downstream of RBPMS in ovarian cancer cells have not been studied." (PMID 35008958, 2022). "However, the biological role of RBPMS in ovarian cancer has not been previously studied." (PMID 35008958, 2022).
glaucoma (5 papers, 2018 to 2025). Increased pressure in the eyeball due to obstruction of the outflow of aqueous humor. "Because RGC death is a hallmark of glaucoma, we examined RGC survival by immunostaining against RNA binding protein (RBPMS) 4 weeks after AAV-Cas13d treatment (Supplementary S4A)." (PMID 40575705, 2025). "We compared the susceptibility of the RGC counts on RBPMS+ cells and the dendritic changes with staining by DiOlistics to the IOP elevation insult in a mouse glaucoma model." (PMID 38649962, 2024). "In the DBA/2J mouse glaucoma model, heavily-labeled POU6F2 RGCs decrease by 73% at 8 months of age compared to only 22% loss of total RGCs (labeled with RBPMS)." (PMID 38698014, 2024). "To determine if the POU6F2-positive RGCs are selectively sensitive to glaucoma, we double stained 4 young DBA/2J (2 months old) mice for POU6F2 and RBPMS and compared these values to 4 aged (8-month-old) DBA/2J mice." (PMID 29370175, 2018).
bladder cancer (4 papers, 2022 to 2025). "We further validate that RBPMS deficiency promotes UC development through facilitating the formation of the c-Fos/c-Jun complex and thus results in the activation of AP-1 in human urinary bladder carcinoma T24 and 5637 cell lines." (PMID 37704624, 2023). "A mechanistic study reveals that RBPMS suppresses bladder cancer cell migration by regulating alternative splicing of ANKRD10, which modulates MYC pathway activity through ANKRD10-2’s function as a transcriptional coactivator." (PMID 40044952, 2025). "In our experimental design, we employed two distinct sgRNAs for RBPMS knockout in bladder cancer cells and conducted comparative RNA-Seq analyses with wild-type cells." (PMID 40044952, 2025). "In our study, we found that RBPMS knockdown led to significant increased AP-1 activity in human urinary bladder carcinoma T24 and 5637 cell lines." (PMID 37704624, 2023). "To investigate the role of RBPMS in the metastasis of UC, we first knocked down RBPMS expression in human urinary bladder carcinoma T24 and 5637 cell lines, and found RBPMS-knocking down cells exhibited increased proliferation ability in comparison to control cells." (PMID 37704624, 2023). "Additionally, reduced levels of RBPMS have been documented in bladder cancer and multiple myeloma cell lines." (PMID 35008958, 2022).
breast carcinoma (4 papers, 2016 to 2023). "Genes MIR124-2, PBX1, SKI, GHSR and RBPMS were reported to be associated with breast cancer, and a gene CYP19A1 was reported to be be associated with endometrial cancer." (PMID 31640538, 2019). "Moreover, reduced levels of RBPMS have been associated with accelerated cell proliferation in breast cancer cells." (PMID 35008958, 2022). "It has been reported that RBPMS inhibited breast cancer cell growth and migration by interacting with c-Fos or SMAD3 in cultured cells and in mouse xenograft models." (PMID 37704624, 2023). "Fu and colleagues reported that the reduced expression of RBPMS promotes the proliferation and migration of breast cancer cells." (PMID 35008958, 2022).
multiple myeloma (4 papers, 2021 to 2024). "According to Rastgoo, the connection between RBPMS and miR-138 played a role in the drug sensitivity of multiple myeloma (MM) with the influence of the enhancer of zeste homolog (EZH2)." (PMID 38305808, 2024).
ocular hypertension (4 papers, 2021 to 2024). Abnormally high intraocular pressure. "Successful induction of ocular hypertension and glaucomatous damage were evaluated via two old-school parameters: IOP measurements and histological RGC soma counts with the pan-RGC marker RBPMS." (PMID 34073191, 2021). "Robust mTORC1 activity, visualized through co-labeling of pS6Ser240/244 and RBPMS, was found in non-injured RGC, and decreased markedly at 2 weeks of ocular hypertension." (PMID 34187514, 2021).
diabetes (2 papers, 2022 to 2024). "RGCs cell death under “diabetes-like” conditions was then analyzed by TUNEL and RBPMS co-staining." (PMID 35168949, 2022).
ischemia (2 papers, 2017 to 2022). A hypoperfusion of the BLOOD through an organ or tissue caused by a PATHOLOGIC CONSTRICTION or obstruction of its BLOOD VESSELS, or an absence of BLOOD CIRCULATION. "Ranibizumab treated retinas showed significantly more RBPMS+ RGCs when compared to the ischemia group (p = 0.027)." (PMID 28800629, 2017).